RBM39 (RNA binding motif protein 39)
Diseases named in the same sentence as RBM39 in open-access papers (continued):
Sharing a sentence is not in itself a finding about the gene and the disease.
cancer (continued). "Collectively, this work identifies the first DUB for RBM39 and elucidates the regulatory functions and the underlying mechanism, providing a possible alternative approach to suppressing RBM39 by inhibiting USP39 in cancer therapy." (PMID 39260689, 2024). "Their findings—bolstered by a specific RBM39-targeting small molecule that they demonstrate preclinical efficacy in a tumour organoid model—contribute to a growing appreciation of metabolic signalling in cancer and ground the development of new precision therapeutics against RBM39-expressing HCC." (PMID 39871876, 2024). "Furthermore, the deletion of KRAS4a or pharmacological inhibition of RBM39 using the splicing inhibitor indisulam has been shown to suppress cancer stem cells." (PMID 38354232, 2024). "In addition to complexing together, JMJD6 and RBM39 exhibit significant correlation of co-dependency in cancer cells, namely, cancer cells have similar dependency on JMJD6 and RBM39 for survival." (PMID 38488852, 2024). "Furthermore, several genes whose expression predicts the poor prognosis of many cancer types and represents potential anticancer targets, i.e., Lgals3, Smox, Ndrg1, Neat1, and Rbm39, were significantly upregulated in most of the KO cell types." (PMID 37809094, 2023). "RBM39 is an essential splicing factor for several cancer cells." (PMID 37666821, 2023). "The manipulation of the autoregulation mechanism using RNA therapeutics could represent a novel strategy to deplete RBM39 from cancer cells." (PMID 37666821, 2023). "By pushing the splicing equilibrium towards the constitutive inclusion of the poison exon, the expression of RBM39 could be shut down, resulting in cancer cell death in a DCAF15-independent manner." (PMID 37666821, 2023). "Accordingly, the control of RBM39 homoeostasis is important for cancer cell survival, and therefore the identification of alternative approaches to lower the intracellular concentration of RBM39 independently of DCAF15 could be beneficial for cancer treatment." (PMID 37666821, 2023). "Our results showed that RBM39 is overexpressed in most cancers." (PMID 35989423, 2022). "Our results suggest that RBM39 plays an important role in cancer immunity." (PMID 35989423, 2022). "With the exception of CHOL, practically all MMRs genes were related with RBM39 expression across cancers, suggesting that RBM39 may protect tumour cell survival by promoting DNA mismatch repair‐related genes expression." (PMID 35989423, 2022). "RBM39 expression was associated with TMB and MSI in 9 and 12 cancer types." (PMID 35989423, 2022). "The findings imply that RBM39 may modulate the pattern of tumour immunity in some cancers by changing the expression levels of these immune checkpoint genes." (PMID 35989423, 2022). "With the deepening of research, a growing number of scholars have generated a thought that RBM39, as a proto-oncogene, is not only closely related to the occurrence and development of a variety of malignant tumors, but also plays a crucial role in the clinical treatment of targeted drugs." (PMID 34389703, 2021). "The in-depth study of these sulfonamides may expand our understanding of the biological functions of RBM39, thereby guiding us to choose the correct target type that is more sensitive to these drugs for better application in cancer treatment." (PMID 34389703, 2021). "The sulfonamide drug Indisulam has been in various cancer clinical trials for several years but its specific targets were unknown until the recent demonstration that it can induce degradation of the RBM39 RNA-binding protein, by tethering to DCAF1513,42." (PMID 34257283, 2021). "Hence, it is necessary for future clinical studies to in-depth study the preferential effect of RBM39 degradation in cancer cells based on the spliceosome genotype, and to further determine the exact function of RBM39 in splicing." (PMID 34389703, 2021).
cancer (continued). "First, although the critical role of RBM39 in the occurrence and development of cancer has been supported by many reports, the current understanding of the mechanism of SPLAMs may be insufficient." (PMID 34389703, 2021). "Moreover, RBM39 is upregulated in various tumors compared with normal tissues in various cancers." (PMID 40302803, 2025). "Our findings may aid to develop a novel cancer therapy focusing on YAP/TAZ/RBM39 interaction." (PMID 39004623, 2024). "This work may provide an alternative strategy for modulating RBM39 for targeted cancer therapy." (PMID 39260689, 2024). "Furthermore, our enrichment analysis suggests that RBM39 may influence the aetiology or pathogenesis of cancer by acting in immune cell infiltration, immune chemokine transduction and immune anti‐infection pathways." (PMID 35989423, 2022). "It has been shown that RBM39, a transcriptional coactivator of activator protein‐1 (AP‐1/Jun), oestrogen receptor and NF‐kB,10, 11, 12 is involved in energy and redox homeostasis and cancer cell proliferation, in addition to its role in vascular endothelial growth factor splicing." (PMID 35989423, 2022). "Therefore, we analysed the expression levels of RBM39 in different types of malignancies and its relationship with prognosis using multiple databases, including TCGA, Cancer Cell Line Encyclopedia (CCLE), Genotype‐Tissue Expression (GTEx), cBioPortal and Human Protein Atlas (HPA)." (PMID 35989423, 2022). "Therefore, small-molecule drugs targeting RBM39 may be an extremely valuable method in the current treatment of various malignant tumors." (PMID 34389703, 2021). "RBM39 indirectly participates in the growth and progression of tumors by regulating the transcription of many tumor-related genes, protein translation, and selective splicing, which provides new ideas and guiding significance for clarifying the pathogenesis of RBM39 in cancer." (PMID 34389703, 2021). "Thus, it is highlighting the significance of RBM39 as targets for cancer therapy." (PMID 34389703, 2021). "The majority of studies investigating this lncRNA have been related to its role in cancer, where it acts to regulate the expression of several microRNAs, including miR-129, miR-194-5p, miR-532-3p, and miR-628-5p, as well as the protein RNA-binding motif protein 39 (RBM39)." (PMID 34420030, 2021). "However, it was also shown that RBM39 degradation is limited to certain cancer cells." (PMID 33261131, 2020). "Furthermore, genes responsible for RNA splicing and mRNA processing including RNA binding protein S1, serine-rich domain, polymerase (RNA) II (DNA directed) polypeptide F and RNA binding motif protein 39 were all down regulated in cancer cells treated with transgenic tomato extracts." (PMID 28448505, 2017). "Many cancer-related genes, such as ZMYND8, ASAH1, and SELENBP1, were found mis-spliced following the degradation of RBM39." (PMID 40223119, 2025). "We finally obtained eight bona fide cancer driver genes, including CEP57, HNRNPL, KLF5, OXA1L, PAFAH1B1, RBM39, SYT13, and TFDP1." (PMID 31925297, 2020). "We uncovered RBM39 as a new splicing activator and RBM10 as a splicing suppressor of RAC1B in LUAD, which greatly facilitates the understanding of RAC1B splicing regulation and functional significance in cancer." (PMID 40548642, 2025). "Previous studies have demonstrated that indisulam could promote RBM39 degradation through the UPS and thus mediate the cytotoxicity to cancer cells." (PMID 36805336, 2023). "Our findings suggest an alternative strategy, namely targeting a cancer-specific arginine-binding factor such as RBM39 rather than broadly limiting arginine in circulation." (PMID 37804830, 2023). "Despite mounting evidence that RBM39 plays a critical role in the development of specific malignancies, no systematic pan‐cancer investigation of RBM39 has been conducted." (PMID 35989423, 2022).
cancer (continued). "Previous studies have reported that immunomodulatory drugs, such as sulfonamides, can recruit the splicing factor RBM39 to the E3 ligase substrate receptor DCAF15, leading to ubiquitination and degradation of RBM39, which resulted in altered RNA splicing and death in some cancer cell lines." (PMID 35989423, 2022). "There are no pan‐cancer studies on the relationship between RBM39 and various cancers." (PMID 35989423, 2022). "In recent years, although there have been relevant reports on the research of RBM39 in tumorigenesis and development, the precise function in specific cancers may not be thorough enough." (PMID 34389703, 2021). "In addition, we noticed seven of them have been included in the latest version of The Network of Cancer Genes35 (KLF5, OXA1L, RBM39, and TFDP1) or CancerMine36 (HNRNPL, KLF5, PAFAH1B1, SYT13, TFDP1), two manually curated cancer gene databases, further confirming our findings." (PMID 31925297, 2020).
tumor (38 papers, 2021 to 2026). "RBM39 degradation causes aberrant splicing and altered gene expression, which suppresses tumor progression in various preclinical models." (PMID 40465651, 2025). "The loss of RBM39 results in aberrant splicing events and differential gene expression within the tumor microenvironment, and as a result inhibits cell cycle progression and induces anti-tumoral effects." (PMID 40227602, 2025). "In particular, RBM39 expression was substantially associated with tumor stage and MSI, which is similar to the findings of this study." (PMID 39023715, 2024). "RBM39 expression was shown to be favourably linked with immune checkpoint gene expression levels in a variety of tumour types, including KICH, LIHC, PAAD and UVM." (PMID 35989423, 2022). "The association between TMB and RBM39 expression was statistically examined using Spearman rank correlation coefficients for each tumour type independently." (PMID 35989423, 2022). "Our study further elucidates the broader tumorigenic applicability of RBM39 and confirms that RBM39 expression is closely associated with the biological processes of immune cells and immune‐related molecules in most tumours." (PMID 35989423, 2022). "RBM39 expression was shown to be substantially linked with tumour stage in four malignancies studied, including LIHC, KICH, THCA and KIRC." (PMID 35989423, 2022). "RBM39 is considered as a novel human tumour‐associated antigen, and its specific immunity has been reported in a variety of tumours." (PMID 35989423, 2022). "In many preclinical models, loss of RBM39 leads to aberrant splicing events and differential gene expression, which inhibit cell cycle progression and lead to tumour regression." (PMID 35989423, 2022). "The degradation of RBM39 causes a disruption of splicing, with increased drug concentrations causing increased splicing alterations, and has been demonstrated to suppress tumor growth in vivo across multiple tumor types." (PMID 40227602, 2025). "We also looked at the association between RBM39 expression and tumour stage." (PMID 35989423, 2022). "Therefore, RBM39 loss may attract innate immune cells to the tumor, which becomes highly inflammatory due to cell damage." (PMID 40962798, 2025). "In addition, RBM39 expression was associated with DNA methylation in almost all tumours." (PMID 35989423, 2022). "Aryl sulphonamides function as molecular glue for the RBM39-DCAF15 E3 ubiquitin ligase complex, facilitating the targeted degradation of RBM39 and resulting in anti-tumor effects." (PMID 40302803, 2025). "Our study found that methylation of RBM39 blocks Indisulam-driven ubiquitination, stabilizes RBM39 protein, and counteracts the drug’s anti-tumor effects." (PMID 40465651, 2025). "RBM39 is a critical RBP involved in transcriptional co-regulation and RNA splicing, and plays an essential role in tumor-associated mRNA and protein expression." (PMID 40465651, 2025). "Clinical studies have shown only modest anti-tumor effects, possibly due to the persistently high expression of RBM39 in NSCLC." (PMID 40465651, 2025). "Our findings suggested that PRMT6-mediated methylation of RBM39 promotes tumorigenicity in tumor cells." (PMID 40465651, 2025). "RBM39 methylation reverses Indisulam-induced mis-splicing, up-regulates oncogene expression, and contributes to tumor progression and drug resistance in NSCLC cells." (PMID 40465651, 2025). "Further analysis of TCGA LUAD cohort data revealed that the expression levels of SRPK1, SRSF1, and RBM39 significantly upregulated in tumor compared to adjacent non‐tumor tissues, and positively correlated with RAC1B levels." (PMID 40548642, 2025). "MTT and colony formation assay showed that PRMT6 overexpression alleviated the inhibitory effects of RBM39 knockout on tumor cell proliferation." (PMID 40465651, 2025). "In conclusion, PRMT6-mediated RBM39 methylation reverses Indisulam-induced oncogene mis-splicing and diminishes its anti-tumor activity." (PMID 40465651, 2025).
tumor (continued). "The sphere formation assay confirmed that PRMT6 overexpression reduced the inhibition of tumor sphere formation caused by RBM39 knockout, while the combination of MS023 and RBM39 knockout led to the formation of even fewer tumor spheres." (PMID 40465651, 2025). "Analysis of The Cancer Genome Atlas (TCGA) database revealed that RBM39 mRNA expression levels were elevated in various tumor types, Moreover, the mRNA expression level of RBM39 was higher in CRC tissues compared with normal tissues." (PMID 40302803, 2025). "Recently, RNA-binding protein 39(RBM39), a critical factor in tumor-targeted mRNA and protein expression, has played a vital role in tumorigenesis and has broad development prospects in clinical treatment and drug research." (PMID 40302803, 2025). "We also examined RBM39 expression in HNSCC tumor and normal tissue types using RSEM expression values." (PMID 40227602, 2025). "illustrated how arginine functions as a molecule possessing second messenger‐like attributes that facilitates the tumor development by modulating the expression of metabolic gene through its specific interaction with RBM39." (PMID 38903537, 2024). "The transcriptional control of ASNA expression by RBM39 results in increased arginine uptake, thereby further enhancing tumorigenicity and promoting the tumor development." (PMID 38903537, 2024). "Our study revealed that indisulam, which targets RBM39 to induce tumor cell apoptosis, is an effective drug for treating T-ALL." (PMID 39044280, 2024). "To confirm that RBM39 is essential for tumor development, we treated 16-week-old L-dKO mice with indisulam." (PMID 37804830, 2023). "We introduced co‐expression analysis and enrichment analysis of genes to investigate the biological functions of RBM39 in tumours." (PMID 35989423, 2022). "We tallied the number of neoantigens in each tumour type and looked at the relationship between RBM39 expression and the number of neoantigens." (PMID 35989423, 2022). "While in the remaining 19 tumours, the expression level of RBM39 in tumours was generally lower than that in normal tissues." (PMID 35989423, 2022). "RBM39 expression leads to different prognostic outcomes for different tumours, which requires further investigation of the specific role of RBM39 in each tumour." (PMID 35989423, 2022). "Our study provides a theoretical basis to gain insight into the role of RBM39 in tumour immunotherapy." (PMID 35989423, 2022). "In contrast, the expression of RBM39 in these eight tumours showed a positive correlation with both Th cells and the subpopulation Tcm of Tregs." (PMID 35989423, 2022). "Based on RBM39’s role in tumorigenesis and tumour immunity, we suggest it can serve as a surrogate prognostic marker." (PMID 35989423, 2022). "We investigated changes in RBM39 expression in 27 tumour tissues by merging data from GTEx normal tissues and TCGA tumour tissues." (PMID 35989423, 2022). "Kaplan–Meier survival analysis showed that patients with low RBM39 expression in both tumours had longer disease‐specific survival." (PMID 35989423, 2022). "We used GSEA enrichment analysis to investigate the biological importance of RBM39 expression in various tumour tissues." (PMID 35989423, 2022). "With its tumor-specific immune function, RBM39 has a unique role in regulating the biological functions of tumor cells." (PMID 34389703, 2021). "In this review, we mainly summarized the possible regulation mechanism of RBM39 involved in tumor, and briefly discussed the molecular function of RBM39 in tumors." (PMID 34389703, 2021). "RNA-binding motif protein 39 (RBM39), as a key factor in tumor-targeted mRNA and protein expression, not only plays a vital role in tumorigenesis, but also has broad development prospects in clinical treatment and drug research." (PMID 34389703, 2021).